HDAC7 (histone deacetylase 7)
Diseases named in the same sentence as HDAC7 in open-access papers (continued):
Sharing a sentence is not in itself a finding about the gene and the disease.
cancer (continued). "Knockdown of HDAC7 led to G1/S arrest in different cancer cells through the upregulation of the cell cycle inhibitor CDKN1A (p21)." (PMID 31482051, 2019). "A significant decrease was also found in the expression levels of crucial epigenetic players UHRF1, DNMT1, and HDAC7, known to inhibit the expression of several tumor suppressor genes in cancer (LogFC<−1.7; p < 0.001)." (PMID 31482051, 2019). "In breast and ovary cancers, HDAC7 is highly expressed in cancer stem cells and it is involved in stem cell maintenance." (PMID 31081251, 2019). "There are only a few reports studying the role of HDAC7 in cancers and even these scarce results were controversial." (PMID 29126425, 2017). "Knockdown HDAC7 in multiple human cancer cell lines resulted in suppression of cell growth by down regulating c-MYC expression and up regulating p21 and p27 expression." (PMID 29126425, 2017). "We also found that the STAT3 acetylation was decreased when exogenous Hdac7 was expressed in human cancer cells, H1299 and A549." (PMID 29126425, 2017). "We show that HDAC7 silencing inhibits cell proliferation and anchorage-independent growth of human cancer cell lines." (PMID 29126425, 2017). "For example, overexpression of HDAC1, HDAC2, HDAC4, HDAC6, and HDAC7 has been observed in various cancers." (PMID 27902771, 2016). "In particular, in 10 cancer cells with relatively high HDAC7 expression, the endogenous ATX expression is low or undetectable (lines 1-9 and line 13)." (PMID 21314984, 2011). "Exogenous over-expression of HDAC7 significantly inhibited ATX expression in these cancer cells, suggesting that HDAC7 is an important negative regulator of ATX expression." (PMID 21314984, 2011). "It was found that HDAC7 expression levels were low in the cancer cells with high endogenous ATX expression." (PMID 21314984, 2011). "In the present paper, we have demonstrated that HDAC3 and HDAC7 are involved in the endogenous ATX expression regulation, which is supported by the loss- and gain-of-function studies in multiple cancer cell lines." (PMID 21314984, 2011). "This indicates that HDAC7 may have diverse and important functions in cancer development and related BPs through its involvement in these pathways and molecular mechanisms." (PMID 40861819, 2025). "Finally, through the method of pan-cancer analysis, we noted that HDAC7 level varies in multiple tumors other than HCC, and there are differences in the prognosis of some tumors." (PMID 40861819, 2025). "Furthermore, the KEGG pathway investigation demonstrated that HDAC7 participates in pathways encompassing "Proteoglycans in cancer", "Regulation of actin cytoskeleton", and "Protein digestion and absorption"." (PMID 40861819, 2025). "Inhibiting HDAC7 can inhibit angiogenesis and cut off oxygen and nutrients from cancer cells." (PMID 39068393, 2024). "Furthermore, quantitative real‐time polymerase chain reaction (qRT‐PCR) analysis on 32 pairs of fresh CRC and adjacent normal tissues confirmed elevated levels of HDAC7 in cancer tissues." (PMID 38827027, 2024). "These suggest that, despite HDAC7-high expressing tumors are heavily infiltrated with immune cells that could kill cancer cells, the effectiveness of immune responses might be significantly abrogated at the level of immune checkpoint signaling." (PMID 39063083, 2024). "As EMT is considered to be vital process in cancer metastasis, we further investigated whether there is any relationship between HDAC7-induced metastasis and EMT-related molecules." (PMID 35277183, 2022). "HDAC7 plays a crucial role in cancers, and is the main drug target of several HDAC inhibitors." (PMID 32376822, 2020). "Interestingly, the unusual activity of the histone deacetylases including HDAC7 has been reported in many types of cancers." (PMID 31482051, 2019). "All these results suggest an oncogenic function of HDAC7 in these human cancers." (PMID 29126425, 2017).
cancer (continued). "We have demonstrated that ATX expression is repressed by HDAC3 and HDAC7 in cancer cells." (PMID 21314984, 2011). "Continued elucidation of mechanisms by which HDAC7 contributes to dysregulated homeostasis will undoubtedly deliver further molecular insights into a range of cancers, inflammatory diseases and metabolic disorders and may ultimately validate HDAC7 as a target in one or more of these conditions." (PMID 35303381, 2023). "Hence, it may be feasible to selectively target HDAC7 for cancer and/or other diseases in which this class IIa HDAC has been implicated." (PMID 35303381, 2023). "But whether HDAC7 regulates EphA2 expression in cancer is unclear." (PMID 32376822, 2020). "In contrast to tumors with high amounts of HDAC7 proteins, the transcriptome signatures of HDAC2-overexpressing cancers are significantly enriched with biological terms previously determined as stemness-associated genes." (PMID 39063083, 2024). "HDAC3, HDAC10, HDAC2, HDAC7, ATAD2B were significantly upregulated in 9, 14, 13, 9, and 10 cancer types, respectively, whereas KAT2B was downregulated in 16 cancer types." (PMID 37553641, 2023). "We explored here the expression profile of HDAC family via Oncomine database, which indicated that HDAC1, HDAC2, HDAC3, HDAC7, HDAC8, and HDAC9 expressed highly in pan‐cancer at transcriptional level." (PMID 34308568, 2021). "HDAC7 levels are increased in RAS‐transformed cells, in which this protein was required not only for proliferation and cancer stem‐like cell growth, but also for invasive features." (PMID 31081251, 2019). "HDAC7 is a member of the HDAC family, and plays an important role in many biological processes and is closely related to the occurrence of cancer." (PMID 30691485, 2019). "We show that an important direct target of HDAC7 is IL24, which is sufficient to suppress the growth of cancer stem‐like cells." (PMID 31081251, 2019). "The Cancer Genome Atlas (TCGA) dataset analysis revealed that HDAC4, HDAC7 and HDAC9 as well as HDAC class I members HDAC1 and HDAC2 is significantly correlated with patient survival." (PMID 31635225, 2019). "HDAC7 enhances the proliferation of HUVEC and cancer cells such as HeLa, HCT116 and MCF-7 probably by stimulating c-Myc and inhibiting p21 and p27 expression." (PMID 29126425, 2017). "The genes categorized into “cancer” group by IPA biofunctions analysis were GPX1, HDAC7, PSME2, MED6, GOLPH3 and MST4 (p<0.05)." (PMID 22438889, 2012). "The target protein(s) of HDAC3/HDAC7 involved in ATX expression regulation remains to be identified, which will be helpful to explain why TSA cannot induce ATX expression in a few cancer cell lines including HT-29, LNcap and Jurkat cells." (PMID 21314984, 2011). "To expand our studies on the role of HDACs in ATX expression, we examined expression levels of HDAC3, HDAC7 and ATX in 13 cancer cell lines." (PMID 21314984, 2011). "Collectively, our data indicate that HDAC3 and HDAC7 play a critical negative regulatory role of in ATX expression, and serve as TSA targets in the ATX induction in cancer cells." (PMID 21314984, 2011). "Differences in HDAC7 expression between patients with different immune subtypes are statistically significant for all tumors (except OV and COAD) and p-values are generally lower in comparison to HDAC2 differences in the same cancers." (PMID 39063083, 2024). "In support of these observations, we found that the most robust and stringent positive associations with cancer stemness were evidenced for HDAC2 expression, whereas a negative association was demonstrated for HDAC7 expression." (PMID 39063083, 2024). "Histone deacetylases (HDACs) play crucial roles in cancers, but the role and mechanism of HDAC7 in NSCLC have not been fully understood." (PMID 35277183, 2022). "HDAC7, a class II HDAC, was found to be involved in cancer development and progression." (PMID 36354673, 2022).
cancer (continued). "Some studies support our results, showing that increased expression of autotaxin in PCa cell lines is mediated by the downregulation of HDAC7 and HDAC3; additionally, HDAC5 is downregulated in human cancer, namely PCa, and decreased expression of HDAC4 increases the growth of PCa cells." (PMID 34833128, 2021). "In addition, we also found that the presence of HDAC7 led to the upregulation of genes related to immune processes (IL16, FCGR2A, IRAK2, CD86 and CD40, among others) and cancer (RASSF4, RAB31, NEDD9 and RASSF2, among others)." (PMID 25675295, 2015). "Interestingly, in cancer stem cells treated with MGCD0103, HDAC7 was significantly downregulated at the protein level, which may suggest a unique feedback mechanism of Hdac7 in early embryos that differs from that observed in cancer cells." (PMID 38317092, 2024). "The transcriptomic profiling indicated that class I HDAC members, including HDAC2, are positively associated with cancer stemness, while class IIA HDAC proteins, represented by HDAC7, show a negative correlation to cancer stem cell-like phenotypes in solid tumors." (PMID 39063083, 2024). "However, previously reported results about the role of HDAC7 in regulating cell proliferation of normal human umbilical vein endothelial cells (HUVEC) and human cancer cell lines are controversial and the functions of HDAC7 in apoptosis of different cells also appear varied." (PMID 29126425, 2017). "Histone deacetylase 7 (HDAC7), a member of the HDAC IIa subfamily (HDAC4, 5, 7 and 9), deacetylates both histones and non-histone proteins and plays important roles in cancer progression." (PMID 36163081, 2022). "In the present paper, we demonstrated a novel ATX expression regulation mechanism in cancer cells, in which HDAC3 and HDAC7 were involved as negative regulators." (PMID 21314984, 2011).
hematological malignancies (6 papers, 2015 to 2023). "HDAC7 loss or dysregulation may lead to B cell-based hematological malignancies." (PMID 37960766, 2023). "Vorinostat, and panobinostat, inhibitors of HDAC class I and II, are effective in patients with hematologic malignancies in phase 1 and phase 2 clinical trials and vorinostat selectively down-regulates HDAC7." (PMID 29721185, 2018). "On the basis of this study, HDAC7 appears to be a promising therapeutic target in these particular types of hematological disease." (PMID 25675295, 2015). "Several reports have described a potential role for HDAC7 in hematological malignancies." (PMID 32913188, 2020).
infection (6 papers, 2018 to 2025). The state of being infected such as from the introduction of a foreign agent such as serum, vaccine, antigenic substance or organism. "To further confirm the involvement of FGF18 in HDAC7-regulated NSCLC progression, we upregulated FGF18 in A549 HDAC7 knockdown cells and downregulated FGF18 in SK-LU-1 HDAC7 overexpressing cells using lentivirus infection." (PMID 35277183, 2022). "Silencing of Hdac7 in vivo ameliorated inflammatory responses and improved survival in an Escherichia coli‐induced acute lung injury model, suggesting that Hdac7 drives systemic inflammation during infection." (PMID 35303381, 2023). "To investigate the role of HDAC7 in ESCC metastasis, we firstly assessed HDAC7 expression in multiple ESCC cell lines, and then we established two stable cell lines via lentiviral infection (HDAC7-overexpressing EC109 cell line and HDAC7 knockdown EC9706 cell line)." (PMID 35595735, 2022). "Furthermore, we showed that how HDAC7 exon skipping can act as a regulator to dynamically control host cell cycle pathway during intracellular infection." (PMID 33060827, 2020). "Furthermore, we upregulated HDAC7 in DNMT3a knockdown LUAD cells and downregulated HDAC7 in DNMT3a overexpression LUAD cells by lentivirus infection." (PMID 39990668, 2025). "Based in the activation of EZH2, HDAC7 and CREBBP is possible that the changes induced by the infection could be genomically imprinted." (PMID 30248353, 2018).
brain diseases (2 papers, 2015 to 2025). "HDAC7 plays an important role in vascular endothelium but loss of HDAC7 does not affect brain disorders." (PMID 26273133, 2015).
hematopoietic cancers (2 papers, 2015 to 2020). "In addition, HDAC7 has been identified as a target gene in hematopoietic tumors in a PiggyBac transposon mutagenesis screening in mice." (PMID 32913188, 2020).
inflammation (2 papers, 2024 to 2026). Aberrant reaction of the microcirculation characterized by movement of fluid and leukocytes from the blood into extravascular tissues. "Beyond identifying an in vivo efficacious molecular probe, our findings expand the current understanding of HDAC7 as an epigenetic regulator and underscore the potential of developing isoform‐selective HDAC7 degraders as therapeutic agents for treating inflammation‐related diseases." (PMID 39049738, 2024).
infectious disease (1 paper, 2024). A disorder directly resulting from the presence and activity of a microbial, viral, or parasitic agent in humans. "Such information can guide our understanding of HDAC7 functions in different cellular contexts and inform strategies for manipulating enzymatic and non-enzymatic activities of this protein in inflammatory and/or infectious diseases." (PMID 39373581, 2024).
neurodegenerative disease (1 paper, 2025). A disorder of the central nervous system characterized by gradual and progressive loss of neural tissue and neurologic function. "Thus, therapies designed to induce astrocyte lysosomal clearance in disease pathogenesis via manipulation of HDAC7 or its downstream target ac-K310 on TFEB may be advantageous for preventing AD and other neurodegenerative diseases." (PMID 39806423, 2025).
HDAC7 also shares sentences with these, for which no sentence is quoted: B-cell acute lymphoblastic leukemia (2 papers); colon cancer (2); metabolic disease (2); renal carcinoma (2); acute erythroid leukemia (1); alcoholism (1); anaplastic astrocytoma (1); bacterial infection (1); benign tumors (1); blood cancers (1); brain cancer (1); breast tumors (1); chronic lymphoid leukemia (1); chronic obstructive pulmonary disease (1); chronic pancreatitis (1); colon adenocarcinoma (1); colorectal tumours (1); cutaneous T-cell lymphoma (1); head and neck squamous cell carcinoma (1); heart failure (1); Huntington disease (1); hyperglycaemia (1); immune diseases (1); kidney cancer (1); liposarcoma (1); liver disease (1); lung (1); lung squamous cell carcinoma (1); malignant glioma (1); medulloblastoma (1).
A further 15 diseases each share a sentence with HDAC7 in 1 paper.